OLFML2B (olfactomedin like 2B)
Diseases named in the same sentence as OLFML2B in open-access papers (continued):
Sharing a sentence is not in itself a finding about the gene and the disease.
tumor (10 papers, 2018 to 2025). "OLFML2B is also strongly correlated with tumor-associated macrophage infiltration, suggesting its role in shaping the tumor microenvironment." (PMID 40135048, 2025). "Studies have shown that OLFML2B is upregulated in multiple cancers, and its high expression is closely associated with poor prognosis, tumor stage, TME remodeling, and immune cell infiltration." (PMID 41208981, 2025). "The correlation analysis between OLFML2B and immune cells showed that it was positively correlated with the degree of macrophage infiltration and highly co-expressed with tumor-associated macrophage markers." (PMID 34868901, 2021). "OLFML2B was highly co-expressed with tumor-associated macrophage markers such as CD14, CD163, CSF1R, ITGAM, and MRC1." (PMID 34868901, 2021). "χ2 tests analysis and Spearman’s correlation analysis revealed that OLFML2B expression was associated with tumor stage (P = 0.001, r = 0.175) and clinical stage (P = 0.027, r = 0.115), which were based on postoperative diagnosis." (PMID 30866865, 2019). "Futhermore, OLFML2B protein may specifically bind to chondroitin sulphate-E in the extracellular matrix, which may be associated with the size of the tumor in clinical pathology." (PMID 30866865, 2019). "OLFML2B expression increases with increasing clinical stage of the cancer, suggesting that this gene promotes tumor progression." (PMID 40135048, 2025). "In the present study, we demonstrate that knockdown of OLFML2B in CAFs attenuates its tumor-promoting effects on HepG2 cell proliferation and invasion, suggesting that OLFML2B is a potential therapeutic target in HCC." (PMID 41208981, 2025). "For instance, GZMA, TCIM, and OLFML2B were significantly clustered in central (C3) and peripheral (C8) regions of the tumor." (PMID 40104502, 2025). "Differential expression analysis showed that LINC01116 and OLFML2B were differentially expressed, with higher expression in tumor tissues (P = 0.045, 0.019)." (PMID 37340445, 2023). "Consistently, we performed RT‐qPCR for OLFML2B in 14 paired tissues, and the result demonstrated that OLFML2B was highly expressed in tumor tissues." (PMID 37676078, 2023). "In 786‐O cells, OLFML2B knockdown greatly inhibited the growth rate of xenograft tumors, and the tumor weight in the OLFML2B knockdown group was significantly lower compared to the control group." (PMID 37676078, 2023). "LINC01116 and the PCG OLFML2B are differentially and highly expressed in tumor tissues (both P ≤ 0.050)." (PMID 37340445, 2023). "We investigated the expression level of OLFML2B from 11,057 samples of tumor and normal tissues (10,327 tumor and 730 normal samples) based on the TCGA database." (PMID 35873458, 2022). "Based on these outcomes, we conjecture that OLFML2B promotes tumor progression by influencing tumor immune response." (PMID 35873458, 2022). "The overexpression of OLFML2B increases the immune scores by upregulation of M2, which has been shown as a tumor promoter to improve the ability of tumor migration and immune escape." (PMID 35873458, 2022). "Simultaneously, a positioning analysis revealed the OLFML2B was mainly focused on the cytoplasm of tumor cells." (PMID 30866865, 2019). "Finally, functional experiments verified that OLFML2B can promote tumor proliferation and metastasis and provide potential therapeutic targets for the diagnosis and treatment of ccRCC." (PMID 37676078, 2023). "Besides, our analysis of TCGA and ICGC cohorts revealed a significant upregulation of OLFML2B expression in tumor samples as compared to normal samples." (PMID 37676078, 2023). "Our results have demonstrated that OLFML2B might have a potential value in tumor diagnosis and prognosis and serve as a marker for immunotherapy." (PMID 35873458, 2022). "On account of former research, we suspect that OLFML2B may influence the development of tumor to change the prognosis." (PMID 35873458, 2022).
tumor (continued). "Meanwhile, OLFML2B is related to immune infiltration, especially in Tregs and M2 in ESCA, KIRC, LIHC, STAD, and LGG, which also indicates that OLFML2B could change tumor immune response and may be a biomarker for immunotherapy." (PMID 35873458, 2022). "Moreover, OLFML2B was highly expressed in metastatic SKCM tissue when compared to the primary tumor tissue based on TIMER2.0." (PMID 35873458, 2022). "Promoter methylation analysis demonstrated that MRC2, OLFML2B, and PLAU were differentially and highly methylated in primary tumor cells compared with normal cells." (PMID 37340445, 2023). "To evaluate the molecular mechanisms of OLFML2B in tumor immunity and oncogenesis, we carried out an analysis of the PPI network of OLFML2B." (PMID 35873458, 2022). "Moreover, MRC2, OLFML2B, and PLAU were differentially and highly methylated between tumor and normal tissues as well as between genders, races and tumor grads." (PMID 37340445, 2023). "The result demonstrated that high expression of OLFML2B predicted deeper tumor invasion and later clinical stage, but it was not correlated with lymph node metastasis and distant metastasis." (PMID 30866865, 2019). "This differential expression suggests that OLFML2B might not be actively involved in tumor biology, as previously hypothesized." (PMID 40104502, 2025). "In addition, knockdown of NDUFA4L2 in HCC cells has been shown to suppress tumor growth and metastasis, which is consistent with our findings of elevated NDUFA4L2, OLFML2B, SEMA5B, and RASL12 expression in HCC tissues and their significant negative correlation with patient survival." (PMID 41208981, 2025). "OLFML2B: Normal tissues exhibit low OLFML2B expression (HPA054136), whereas tumor tissues show no detectable expression." (PMID 40104502, 2025). "This led to the selection of seven antigens found to be overexpressed in both mouse MM tumor lines under investigation and that were nearly absent in all other mouse normal tissues: KIF20A, KIF2C, MMP9, MNDA, OLFML2B, TROAP, and ULBP1." (PMID 31428586, 2019).
OLFML2B also shares sentences with these, for which no sentence is quoted: breast carcinoma (2 papers); COVID-19 (2); adrenocortical carcinoma (1); bladder urothelial carcinoma (1); breast invasive carcinoma (1); carotid atherosclerosis (1); cervical cancer (1); lung adenocarcinoma (1); myeloma (1); neuroblastoma (1); ovarian carcinoma (1); ovarian serous cystadenocarcinoma (1); sarcoma (1); stomach adenocarcinoma (1); stomach neoplasms (1); thyroid carcinoma (1); uveal melanoma (1).